NR1H4 (nuclear receptor subfamily 1 group H member 4)
Diseases named in the same sentence as NR1H4 in open-access papers (continued):
Sharing a sentence is not in itself a finding about the gene and the disease.
microvillous inclusion disease (1 paper, 2025). "This led to the discovery of three new conditions; PFIC 4, 5, and 6, caused by mutations in TJP2 (tight junction protein 2), NR1H4 (farnesoid X receptor), and MYO5B (linked to microvillous inclusion disease), respectively." (PMID 39927143, 2025).
renal cell carcinoma (1 paper, 2022). "Due to KIRC is the most common subtype of renal cell carcinoma, we analyze the expression pattern of NR1H4 in CPTAC samples and GEO samples with ccRCC, which was identical with the result before." (PMID 36123627, 2022). "The results showed that cell cycle, mismatch repair, DNA replication, nucleotide excision repair, renal cell carcinoma, mTOR signaling pathway were enriched in the NR1H4 highly expressed group, which provides a potential mechanism whereby NR1H4 might regulate the progression of ccRCC." (PMID 36123627, 2022).
tumor (183 papers, 2008 to 2026). "The bile acid induction of epithelial cell proliferation by bile acid receptor-dependent pathways, namely NR1H4, suggests the loss of intestinal NR1H4 leads to increased intestinal epithelial cell proliferation and tumor development." (PMID 41043692, 2025). "The results showed there was a significant correlation between NR1H4 expression and the most of marker set of monocyte, Tumor-associated macrophages (TAM), M2 macrophage, Th2, Tfh, Treg and T cell exhaustion." (PMID 36123627, 2022). "Farnesoid X receptor (FXR), a transcriptional factor encoded by NR1H4, serves as a tumour suppressor in HCC." (PMID 35999582, 2022). "Mechanistically, tumor‐associated signaling pathways were enriched in the NR1H4 overexpression group and si-NR1H4 could induce the downregulation of Cyclin E2 (CCNE2)." (PMID 36123627, 2022). "In CCRCC, NR1H4 functions as a mediator of tumor immunity and plays a key role in tumor metastasis and drug resistance." (PMID 40656893, 2025). "NR1H4 and IL4R are promising immune-related diagnostic biomarkers for OCCC, with potential roles in neutrophil-mediated tumor microenvironment modulation." (PMID 40656893, 2025). "In the present study, we reported that NR1H4 was overexpressed in ccRCC and high expression of NR1H4 is important to promote tumor progression." (PMID 36123627, 2022). "Using UALCAN, we also found that promoter methylation of NR1H4 in sample types, patient age, patient gender, individual cancer stages, tumor grade and nodal metastasis status was reduced than normal tissues." (PMID 36123627, 2022). "Our result provides insights in understanding the pathologic role of NR1H4 in promoting tumor progression, as well as its potential value as a new diagnostic biomarker and therapeutic target for ccRCC." (PMID 36123627, 2022). "GSE167093 was used to investigate the correlation between NR1H4 expression and clinicopathological features of ccRCC, we found higher expression levels of NR1H4 significantly contributed to tumor stage." (PMID 36123627, 2022). "The results of IHC revealed the higher expression of NR1H4 in ccRCC samples in contrast to tumor adjacent samples." (PMID 36123627, 2022). "A Immunohistochemistry assay showed the higher expression of NR1H4 in ccRCC tumor tissues when compared with tumor adjacent tissues." (PMID 36123627, 2022). "TIMER algorithm was performed in TIMER2.0 database to investigate the relationship between NR1H4 expression and tumor-infiltrating lymphocytes in ccRCC." (PMID 36123627, 2022). "Our study indicated that NR1H4 might be a potential tumor biomarker and therapeutic target for ccRCC which could promote cancer cell proliferation, migration and invasion via regulating CCNE2." (PMID 36123627, 2022). "Studies on the function of NR1H4 in tumor progression are increased in recent years." (PMID 36123627, 2022). "Moreover, the correlation between NR1H4 expression and the marker genes of immune cells implicate the role of NR1H4 in regulating tumor immunology in ccRCC." (PMID 36123627, 2022). "In addition, TCGA samples exhibited that NR1H4 was upregulated in all the variables compared to the normal, including patient’s age, patient’s gender, individual cancer stages, tumor grade, nodal metastasis status." (PMID 36123627, 2022). "Knockdown of NR1H4 can also attenuate the expression level of SOCS1 and SOCS2 after ZINC24469384 treatment, and the decrease of SOCS2 is sharper than SOCS1, These data indicated that SOCS2 may play more important role in NR1H4 induced anti-tumor effects." (PMID 30787420, 2019). "Statistical analysis with ANOVA multiple comparisons test showed that the expression of NR1H4 and SOCS2 in tumor were lower than normal tissues in two cancer types." (PMID 30787420, 2019).
tumor (continued). "Further, we employed SCENIC to predict transcription patterns of tumor cells, finding a series of key TFs of HCC tumorigenesis, such as TFs in regulation of cell dedifferentiation (SPI1, HMGB3, and YBX1) and in abnormal bile acid metabolism (NR1H4, NR1I3, FOXA3 and DDIT3)." (PMID 37985711, 2023).
cancer (124 papers, 2011 to 2026). A tumor composed of atypical neoplastic, often pleomorphic cells that invade other tissues. "Correlation analysis and cell biological experiments showed that NR1H4 expression was positively associated with Cyclin E2 and CDK2, which indicated NR1H4 may play its oncogenic role in cancer by regulating CCNE2." (PMID 36123627, 2022). "Farnesoid X receptor (NR1H4/FXR), functioning as a bile acid receptor (BAR), is also a nuclear receptor implicated in various cellular processes in cancer." (PMID 39543094, 2024). "This suggested that NR1H4-SOCS signal was likely to play a substantial role in anti-cancer effect after ZINC24469384 treated." (PMID 30787420, 2019). "Abnormal expression of NR1H4 has been reported in various cancers." (PMID 36123627, 2022). "According to previous reports, inhibition of NR1H4 has an anti-cancer effect." (PMID 36123627, 2022). "Recently, the research on the role of NR1H4 in cancer has been investigated in several tumors." (PMID 36123627, 2022). "Knockdown of NR1H4 significantly suppressed cancer cell proliferation, migration and invasion." (PMID 36123627, 2022). "More experiments are needed to define the role of the NR1H4 in cancer." (PMID 33397428, 2021). "Farnesoid X receptor (NR1H4/FXR) functions as a scavenger of lipid peroxide products and drives the proliferation and metastasis of various cancers." (PMID 39543094, 2024). "NR1H4, also known as Farnesoid X Receptor (FXR), acts as a nuclear receptor that can be activated by binding with bile acids, and FXR is highly correlated with the progression of cancers." (PMID 35563650, 2022). "Transcription factor targets included NR1H4, ZMYM2 and ZNF436, which might be metabolism-related and cancer-related factors." (PMID 35410157, 2022). "Similarly, the expression of FXR (NR1H4) was downregulated in cancer tissues compared to the non-neoplastic tissues." (PMID 36998446, 2023).
infection (26 papers, 2009 to 2025). The state of being infected such as from the introduction of a foreign agent such as serum, vaccine, antigenic substance or organism. "Infection also down-regulated genes of the FXR pathway (e.g., NR1H4, FABP6, APOA1, SLC10A2), indicating disruption of the bile acid absorption in ileum." (PMID 26738723, 2016). "The liver X receptor α (LXRα, also known as NR1H3) and the farnesoid X receptor (FXR, also known as NR1H4) interact with the retinoid X receptor (RXR) and play essential roles in fatty acid, cholesterol, sterol, bile acid and glucose metabolism, and both were observed downregulated upon infection." (PMID 33314005, 2021). "However, the expression of Pkd2, Pkhd1, Kif12, Cadherin16 and Socs3, which are known as HNF-1β target genes, did not change (data not shown), and only a few genes, including NR1H4, MITF, SLC3A1, and SLCO4C1, were significantly upregulated 9 h after Ad-HNF1B infection." (PMID 27196561, 2016).
kidney disease (24 papers, 2015 to 2025). "Nr1h4 is known to have a role in several metabolic processes in the liver, and it has been shown to curtail ER stress in liver injury and kidney disease." (PMID 38609183, 2024). "This review focuses on the functional role of the farnesoid X receptor (FXR, NR1H4) in kidney homeostasis and kidney diseases." (PMID 36737665, 2023). "We also found novel cell-type-specific TFs, such as Nr1h4 for PTinj_1, Nfyc for DediffPT_1, and Foxn3 for PTinj_2, which are interesting candidates for studying their roles in renal disease development and warrant validation in future studies." (PMID 37023747, 2023). "Healthy controls and kidney disease samples showed strong expression of DNL genes, including ACSS2, NR1H3 (liver X receptor α [LXRA]), NR1H4 (farnesoid X receptor [FXR]), SREBF1, SCAP, PLIN2, PLIN5, ACACAB, ATP citrate lyase (ACLY), and FASN in PT cells and some other tubule cells." (PMID 38051585, 2023).
adenocarcinoma (10 papers, 2010 to 2025). A common cancer characterized by the presence of malignant glandular cells. "Caco-2 cells are derived from an immortal adenocarcinoma in which expression of NR1H4 and FABP6 differs from primary colonic epithelial cells." (PMID 40586821, 2025).
NR1H4 also shares sentences with these, for which no sentence is quoted: metabolic disease (160 papers); steatosis (122); diabetes (101); type 2 diabetes (59); hyperlipidemia (54); Cirrhosis (44); inflammatory bowel disease (41); Pruritus (30); Hyperglycemia (28); Glucose intolerance (24); Hypercholesterolemia (21); pancreatic cancer (20); primary sclerosing cholangitis (20); lipid metabolism disorders (18); portal hypertension (17); Crohn disease (16); renal fibrosis (15); inflammation (14); liver (14); fibrosis (12); hypertriglyceridemia (12); intestinal diseases (12); cardiovascular diseases (11); glomerulosclerosis (11); Impaired glucose tolerance (11); intestinal cancer (11); non-small cell lung carcinoma (11); COVID-19 (10); injury (10); liver cirrhosis (10).
A further 251 diseases each share a sentence with NR1H4 in 9 papers or fewer.